FOXP3 (forkhead box P3)
Diseases named in the same sentence as FOXP3 in open-access papers (continued):
Sharing a sentence is not in itself a finding about the gene and the disease.
asthma (continued). "GWAS of asthma have successful identified genetic susceptibility; however, little information about the X chromosome has been reported, and no information about the association of FOXP3 SNPs on allergic diseases has emerged." (PMID 27965764, 2015). "The effect of Budesonide and Formoterol was tested “in vitro” on IL-17A, RORγ(t) and FOXP3 expression in cultured T-lymphocytes from mild-moderate asthma/persistent rhinitis patients, and on nasal and bronchial epithelial cells stimulated with NW and Ss from mild-moderate asthma/persistent rhinitis." (PMID 23573194, 2013). "To better understand the role of IL-17A in asthma and rhinitis we investigated: 1) the levels of IL-17A in sputum supernatants (Ss), in nasal wash (NW) and in plasma (P), and 2) the levels of intracellular IL-17A, RORγ(t) and FoxP3 expression in peripheral T-lymphocytes." (PMID 23573194, 2013). "In a murine model of ovalbumin-induced asthma, inhibition of lung inflammatory process, by S. mansoni eggs or by the S. mansoni antigens, Sm22.6, PIII, and rSm29 were associated with an increase in the number of CD4+CD25+Foxp3+ T cells and high levels of IL-10 production." (PMID 23209879, 2012). "Eligible studies included pediatric populations with asthma or wheeze phenotypes assessing predefined genetic (ORMDL3, GSDMB) or epigenetic (AHRR, FOXP3, CpG loci) markers and reporting odds ratios (ORs) or sufficient data for their derivation." (PMID 41682911, 2026). "NECs cannot avoid transmitting information via CD4+CD25+Foxp3+ Tregs through TSLP/TSLPR, similar to the lower airway in asthma." (PMID 40051629, 2025). "↑ T lymphocytes (CD3+), Treg (CD4+CD25+FOXP3+), Tc (CD8+), and NK cells (CD3–CD16+CD56+). ↓ activated T cells (CD25+/CD69+). ↑ immune modulation in asthma." (PMID 40352259, 2025). "To investigate the effect of shikonin on T-cell populations in asthma mice, we evaluated the phenotypes of CD4+ cells in lung tissues by analyzing the expression of IFN-γ, FOXP3, IL-4, and IL-17 via flow cytometry." (PMID 39444792, 2024). "In a murine asthma model, oral administration of PCBL induced an increase in the number of CD4+CD25+FOXP3+ lymphocytes in intestinal lamina propria and respiratory tract mucosa." (PMID 35812388, 2022). "Pro-inflammatory cytokine-secreting Tregs such as IFN-γ-producing FOXP3+ cells, IL-4-producing FOXP3+ cells, and IL-17-producing FOXP3+ cells are also noticed in asthmatic patients, which are strongly correlated with the severity of asthma and might be insensitive to corticosteroids." (PMID 35757774, 2022). "Over-expression of miRNA-221-5p induced the protein expression of FOXP3, and suppressed that of SOCS1 and RORγt in in vitro model of asthma." (PMID 34863307, 2021). "OVA challenge reduced the percentage of Tregs with an increased expression of Foxp3 and STAT5; notably, metformin reversed this trend in obese asthma." (PMID 33421348, 2021). "IL-17A-producing CD4+Foxp3+ Treg cells are known to be involved in various diseases, including COPD and asthma." (PMID 32411140, 2020). "Therefore, our present study suggested that it is likely that intraperitoneal administration of α‐GalCer prior to the development of asthma disorder, which can promote the generation of lung CD4+ FoxP3+ Treg cells by the activated iNKT cells, may have potential as a therapeutic method for asthma." (PMID 30421497, 2019). "The treatment increased the percentage of FoxP3+ T cells within CD4+ T cells significantly, from about 40% to about 65%; thus, the GCs did induce an increase in the Treg subset in the equine asthma model." (PMID 30845709, 2019). "We also compared the proportion of sialyl LeX positive FOXP3+ Treg cells among total CD4+ T cells, and found that it was slightly lower in asthma children compared with healthy controls (p = 0.16), despite not reaching statistical significance." (PMID 31222115, 2019). "We sought to identify CpG sites in the Foxp3 and IL10 genes that have higher DMRs in children with asthma exposed to AAPs." (PMID 29317916, 2018).
asthma (continued). "It has been reported previously that DC10 treatments reverse the disease phenotype in OVA and house dust mite models of asthma, wherein they suppress the allergen-specific T cell response, inducing Th2 cells to differentiate into CD4+CD25+Foxp3+ Treg." (PMID 29293622, 2018). "Previous studies showed that both USP21 and PIM2 are regulators of GATA3 and FOXP3 expression, respectively, in Treg cells, so we measured the expressions of USP21 and PIM2 in Treg cells from patients with asthma and healthy subjects." (PMID 30013989, 2018). "Another study has shown that patients with asthma have normal numbers of CD4+CD25hi and CD4+CD25hi FOXP3+ Tregs in peripheral blood compared to healthy individuals, although the expression of the FOXP3 protein was attenuated." (PMID 28589115, 2017). "Consequently, Foxp3 methylation hints towards worsening of asthma pathology due to impaired production and functioning of T regulatory cells, thus providing a very interesting mark that can be targeted while exploring potential epigenetic therapeutic options against asthma." (PMID 27293973, 2016). "This study reveals that PCF can downregulate RORγt and elevate Foxp3 expression, reduce IL-6, IL-17, IL-23, TGF-β in BALF, thus restore the balance of Th17/Treg, improve airway inflammation and reduce asthma symptoms." (PMID 26178910, 2015). "The experimental asthma mice had higher CD4+IL-17A+ cell numbers and decreased CD4+Foxp3+ cell numbers in BALF as compared to NC mice (p < 0.01)." (PMID 26612993, 2015). "Quantitative and functional impairment of pulmonary CD4+CD25+Foxp+ Treg cells in pediatric asthma patients has been observed, demonstrating that CD4+CD25+FOXP3+ Treg cells can reverse established allergic airway inflammation and prevent airway remodeling." (PMID 26565810, 2015). "Yet another insight from the asthma research relates to the distinction between CD4+FoxP3−IL-10+ Tr1 cells and CD4+FoxP3+IL-10− Treg cells." (PMID 25852682, 2015). "A study among school children with and without asthma living in areas with contrasting levels of ambient air pollution showed that pollution is associated with increased methylation of CpG islands in the Foxp3 locus, reduced T reg cell function and increased asthma severity scores." (PMID 23663440, 2013). "Since we observed decreased Treg function in asthmatic twins, we next assessed the relative levels of FOXP3 protein and transcription in Treg from MZT discordant for asthma." (PMID 23226205, 2012). "Children living in more highly polluted communities had changes in DNA methylation of FOXP3 and ACSL3 genes, both important in asthma morbidity and symptoms in children." (PMID 22591701, 2012). "A direct link between CD4+CD25+FoxP3+Tregs and suppression of AHR in asthma has now been demonstrated in vivo." (PMID 19769993, 2010). "Conversely, genes such as FOXP3 and STAT4 exhibited stronger staining intensity in the control group, indicating distinct roles of these genes in the pathophysiological mechanisms of asthma." (PMID 40309741, 2025). "Differentiation of FOXP3 and IL10 DNA methylation was identified in the PBMC of children with asthma who were exposed to NO2, CO, and PM2.5 in the long term (2 years), and the methylation of FOXP3 promoter augmented because of all three types of pollutants mentioned." (PMID 33781317, 2021). "Our results showed that C57BL/6 mice presented the highest lung levels of CD4+CD25+Foxp3+ cells in the presence or absence of allergen provocation and failed to develop asthma characteristic features following allergen provocation." (PMID 34924814, 2021). "The observed differences in the frequencies of Treg cell subtypes associated with the susceptibility of the animals to experimental asthma suggest that CD4+CD25+Foxp3+ and IL-10-producing CD4+ Treg cells may play different roles in asthma control." (PMID 34924814, 2021).
asthma (continued). "Over-expression of miRNA-221-5p suppressed the protein expression of SOCS1 and RORγt and induced that of Foxp3 in in vitro model of asthma, compared with negative group." (PMID 34863307, 2021). "Foxp3+ Treg cells can inhibit Th17- and Th- cell-mediated inflammatory responses and prevent bronchial AHR and airway inflammation both in animal models and in patients with asthma; the functions of Foxp3+ Treg cells are impaired in asthma." (PMID 33806085, 2021). "IL-17 producing Foxp3+ Treg (Th17 like Treg) cells were significantly elevated in the lungs of the HDM-induced asthma mice, whereas Treg cells did not express Th17-type cytokines not altered." (PMID 34497608, 2021). "Jurkat cells inducibly overexpressing FOXP3 for 2 days (FOXP3 2-day cells) are similar to CD4+CD25+CD127−/low T cells from subjects without asthma and FOXP3 5-day cells are similar to Tregs from asthmatic subjects." (PMID 34072455, 2021). "Down-regulation of miRNA-221-5p induced the protein expression of SOCS1 and RORγt and suppressed that of Foxp3 in in vitro model of asthma, in comparison with negative group." (PMID 34863307, 2021). "Therefore, the effects of RORγt and SOCS1/3 acutely exacerbated RSV infection of asthma Our findings confirmed that Over-expression of miRNA-221-5p suppressed SOCS1 and RORγt protein expression and induced Foxp3 protein expression in vitro model of asthma." (PMID 34863307, 2021). "Hence, metformin treatment increased the percentage of Tregs and its related transcript factors Foxp3 and STAT5, to provide a vital function in alleviating airway inflammation in obese asthma." (PMID 33421348, 2021). "Exposure to OVA resulted in the upregulation of GATA-3 and RORγt protein expression and downregulation of Foxp3 expression in mice, suggesting that OVA might induce asthma through the GATA-3, RORγt, and Foxp3 signaling pathways." (PMID 33806085, 2021). "Data on the frequency of Foxp3 Treg cells in murine experimental asthma are not easily compared, since they either lack nonallergic control mice and Foxp3 intracellular staining on CD4+CD25+ cells or use only one mouse strain." (PMID 34924814, 2021). "Foxp3 is known to activate Tregs and suppress NKT cells in asthma." (PMID 33291534, 2020). "However, studies in animal models of allergic airway inflammation have investigated a fair amount of preclinical and clinical research, which included the key roles of FOXP3+ Treg, IL-10, and TGF-β in asthma prevention." (PMID 33267824, 2020). "In the current study, FOXP3 expression did not significantly differ between patients with asthma and healthy subjects." (PMID 30116273, 2018). "Foxp3-EGFP-expressing adenovirus or EGFP control adenovirus was administered intratracheally (i.t.), followed by challenge with ovalbumin (OVA) or cockroach extract to induce asthma." (PMID 27633092, 2016). "Our initial hypothesis was that, similar to H. pylori-mediated protection from asthma, reduced EAE severity could be due to the induction of an enhanced Foxp3+ Treg population." (PMID 25762984, 2015). "Treatment with PCF downregulates RORγt, elevates Foxp3 expression, reduces interleukins-6, -17, -23 and TGF-β in bronchoalveolar lavage fluid, thus restoring Th17/Treg balance, improving airway inflammation and reducing asthma symptoms." (PMID 26178910, 2015). "To check whether the beneficial effects of Pam3Cys treatment on asthma manifestations could have been mediated by an increased presence of Treg cells, we measured by flow cytometry the numbers of CD4+CD25+Foxp3+ cells in the BAL infiltrates." (PMID 23393567, 2013). "The present study demonstrates that BUD, an inhaled corticosteroid widely used for the management of bronchial asthma, controls asthma inflammation modulating ICOS, cell survival, Foxp3 and IL-10 expression differently in CD4+/CD25− and in CD4+/CD25+ cells in peripheral blood." (PMID 23251336, 2012).
asthma (continued). "In a small (n = 4) sample set, we found that these twins had some, but not full, CpG methylation in the FOXP3 locus (mean 34%: range 31–38%) vs. twins with no asthma and no SHS exposure (mean 7%: range 3–12%)." (PMID 23226205, 2012). "To address this hypothesis, we conducted cellular and molecular studies at the functional, protein, transcript and epigenetic level of FOXP3 and IFNγ in purified T cell subsets among MZT discordant for asthma." (PMID 23226205, 2012). "Most of childhood-onset asthma is driven by type 2 immune response, without sufficient regulation by type 1 (Th1 cells) and type 3 (RORγt+ Foxp3+ Treg) responses, and can be defined by the high level of immunoglobulins E (IgE) in the serum and eosinophilic airway inflammation." (PMID 36685549, 2022). "miRNA-221-5p may play critical roles in driving the differentiation of Th17/Treg ratio via RORγt/Foxp3 by Targeting SOCS1, reduced the function of Th17 cells by directly inhibiting RORγt/SOCS1 and promoted the function of Treg cells via Foxp3/ SOCS1 in asthma." (PMID 34863307, 2021). "Higher average exposure to polycyclic aromatic hydrocarbons is associated with higher DNA methylation at several CpG sites on the FOXP3 locus of peripheral blood mononuclear cells (PBMCs), and Treg cells, which are observed more clearly in children with asthma than in children without asthma." (PMID 34754417, 2021). "The inhibition of FOXP3 attenuated the effects of miRNA-221-5p on the inhibition of IL-6, IL-17, IL-21 and IL-22 levels, and promotion of IL-10, IL-35 and TGF-β levels in in vitro model of asthma following anti-miRNA-221-5p, in comparison with anti-miRNA-221-5p group." (PMID 34863307, 2021). "Wild-type DC10 ablated the OVA-asthma phenotype via induction of Foxp3+ Treg responses, but CD40-/- DC10 had no discernible effects on primary facets of the phenotype (e.g., IL-5, IL-9, IL-13 levels, IgE & IgG1 antibodies; p>0.05) and were ≤40% effective in reversal of others." (PMID 33793599, 2021). "However, simple exposure to 1 μg LPS without asthma induction (LPS/PBS) did not significantly affect Foxp3, GATA3, or ROR-γt mRNA levels nor IL-10, TGF-β, IL-4, IL-5, IL-13, or IL-17 levels (p > 0.05) compared to those of Control mice." (PMID 33072079, 2020). "The current study data regarding FOXP3 expression by PBMCs indicated that there may be no functional impairment in Treg cells of patients with asthma." (PMID 30116273, 2018). "The frequency of Foxp3+IL-10+ CD4+ T cells did not correlate with asthma severity (data not shown)." (PMID 29507584, 2018). "With therapeutic effects of TCs on experimental asthma, we found that TCs could increase the systemic and local production of TGF‐β and altered the proportion of Treg cells and increase the transcription factor Foxp3 mRNA." (PMID 28524369, 2017). "Therefore, the anti-asthmatic effects of Ad Foxp3-EGFP on OVA-induced asthma were not mediated by Treg cells." (PMID 27633092, 2016). "Furthermore, when Tregs were depleted by diphtheria toxin in Foxp3DTR mice, the anti-asthmatic functions of Foxp3 were not altered in OVA-challenged asthma models." (PMID 27633092, 2016). "Irrespective of the exposure or disease status, methylation of several asthma and allergy-related genes changed over time (IL-4, IL-13, ORMDL3, RAD50), indicating their involvement in developmental processes, while Treg-related genes (FOXP3, RUNX3) remained unchanged." (PMID 26052354, 2015). "Accordingly, the methylation of CpG islands located in the promoter and in intronic regions of FOXP3 in Treg cells was higher in asthmatics relative to children without asthma, with a greater effect being observed in children who were exposed to high levels of pollution." (PMID 27965764, 2015). "Finally, it is necessary to study other genes important in allergies and asthma that could be epigenetically modified, with repeated measurements performed for these genes as well as IFN-γ and Foxp3 to assess the durability of these changes over time." (PMID 23009259, 2012).
asthma (continued). "Interestingly, there was a trend for higher CD25+FOXP3+ cell number in neonates with (n = 24) compared those without (n = 34) maternal asthma (median [range] = 2.75 [0.10–7.80] vs. median [range] = 3.85 [1.00–7.30]); p = 0.07)." (PMID 19586545, 2009). "In conclusion, miRNA-221-5p may play critical roles in driving the differentiation of Th17/Treg ratio via RORγt/Foxp3 by Targeting SOCS1, reduced the function of Th17 cells by directly inhibiting RORγt/SOCS1 and promoted the function of Treg cells via Foxp3/ SOCS1 in asthma." (PMID 34863307, 2021). "For example, a Chinese study conducted on a small group of asthmatic patients with and without asthma showed decreased CD4+ CD25+ FOXP3+ Treg levels and lower FOXP3 mRNA expression in asthmatic patients compared to healthy children." (PMID 36981683, 2023). "In this study, our results suggest that Foxp3 expression in lung epithelial cells, and not in Tregs, inhibited OVA- and cockroach extract-induced asthma." (PMID 27633092, 2016). "We did not observe a significant difference between asthma and controls with respect to the incidence of other Foxp3 or IL-10 positive cells: CD4+Foxp3+, CD4+Foxp3+CD25+, CD4+IL-10+IL-4- or CD4+Foxp3+IL-10+." (PMID 25132806, 2014). "SHS and AAP are not the only factors known to influence asthma, nor are IFN-γ and Foxp3 the only genes relevant to the development and exacerbation of the disease; other factors, both environmental and genetic, are currently under investigation." (PMID 23009259, 2012). "We also found a lower proportion of the sialyl LeX positive cells among FOXP3+CD25+ Treg cells in asthmatic children, and significantly fewer numbers of sialyl LeX-positive Treg cells in children with moderate-to-severe asthma, in comparison with non-asthmatic children." (PMID 31222115, 2019). "However, there were no significant changes in IFN-γ, FOXP3, and IFN-γ/IL-4 ratio in asthma group treated with dexamethasone compared with untreated asthma group." (PMID 28824424, 2017). "Furthermore, while there was a trend for higher CD25+FOXP3+ cell number in neonates with maternal asthma, CD25+ cell suppressive capacity was similarly reduced in neonates with and without maternal asthma." (PMID 19586545, 2009). "Although there is no direct evidence yet for this hypothesis in asthma, in other contexts HLA-G has been shown to suppress dendritic cells and T cells that participate in inflammation, and to activate CD4+CD25+FoxP3+ regulatory T cells that can suppress cells that participate in airway inflammation." (PMID 23327606, 2013).